INS (insulin)
Diseases named in the same sentence as INS in open-access papers (continued):
Sharing a sentence is not in itself a finding about the gene and the disease.
metabolic syndrome (continued). "TRT can improve multiple cardiovascular risk factors, including blood glucose control, insulin sensitivity, dyslipidemia, and central obesity." (PMID 33061966, 2020). "The allele T of rs13412852 in LPIN1 is associated with lower body mass index and insulin levels, thus it is possibly considered as a protector for the metabolic syndrome alterations." (PMID 30986988, 2019). "Tesaglitazar is part of a larger family of PPARα/γ dual agonists, which effectively improve insulin sensitivity and dyslipidemia in patients with diabetes and obesity-associated dysmetabolism." (PMID 31725756, 2019). "The increase in insulin signaling pathway genes in high BMI subjects further strengthens the association between an underlying metabolic syndrome in those subjects and impacts on the microbiome." (PMID 30654751, 2019). "From this viewpoint we regard the significant elevation of IGF-1 in a low baseline IGF-1 subgroup as a positive change, which is possibly associated with a reduced risk of developing the metabolic syndrome and with improved insulin sensitivity." (PMID 31191190, 2019). "Both IGFBP1 and 3 are related to insulin levels, fat accumulation, and have been linked to the metabolic syndrome, which also affects equids." (PMID 31022261, 2019). "As skeletal muscle is the primary tissue responsible for insulin-dependent glucose uptake, sarcopenia is associated with systemic insulin resistance, which progressively induces metabolic syndrome." (PMID 31799199, 2019). "The adiponectin/leptin ratio was reported to be associated with insulin sensitivity, and our study in agreement with previous document demonstrated that this ratio contributed to the metabolic syndrome." (PMID 31341853, 2019). "There is ample evidence that links sugar-sweetened beverage consumption to adverse effects on metabolic risk factors, such as dyslipidemia and insulin resistance." (PMID 31052523, 2019). "The metabolic syndrome (MetS) is nowadays a major and growing public health and clinical challenge worldwide, encompassing many underlying dysfunctional mechanisms such as insulin resistance, inflammation, hormonal changes, and physical activity." (PMID 31766373, 2019). "In obese children, further weight gain is associated with a significant reduction in insulin sensitivity along with worsening of all components of the metabolic syndrome." (PMID 31474943, 2019). "We discuss how disruption of the insulin signal is associated with various metabolic disorders of glucoses and lipids that constitute both the metabolic syndrome and NAFLD." (PMID 30642126, 2019). "The mRNA expression of LPIN1 in liver and adipose tissue have positive associations with body mass and insulin sensitivity, and its polymorphisms have been associated with metabolic syndrome." (PMID 30986988, 2019). "TLR2-deficient mice were shown to have improved insulin sensitivity and reduced diet-induced metabolic syndrome." (PMID 31507457, 2019). "We will provide context for how disruption of the insulin signal is associated with various metabolic disorders of glucose and lipid that constitute the metabolic syndrome and NAFLD." (PMID 30642126, 2019). "We gathered data from users who entered PGHD on body weight, blood pressure (BP), blood glucose levels, 10-year cardiovascular disease (CVD) risk, metabolic syndrome risk, medication schedule, insulin, and allergy." (PMID 29631989, 2018). "Disruption of insulin production or transduction of its signal is intimately associated with generation of metabolic syndrome." (PMID 30619467, 2018). "Pearson correlation was assessed between insulin level and each of the diagnostic components of metabolic syndrome (MetS-DCs) with adjustment of age." (PMID 29724734, 2018). "Human studies report that SPI improved insulin sensitivity (a known risk factor for liver steatosis) in postmenopausal women with abdominal obesity and metabolic syndrome." (PMID 29757972, 2018).
metabolic syndrome (continued). "Many reports have manifested that T2DM is closely in connection with dyslipidemia due to the decrease in sensitivity of fat cell membrane receptors to insulin, leading the weakening of antifat effect and causing the accumulation of fatty acids in the blood." (PMID 30595798, 2018). "Factors that improve liver enzymes include the beneficial effects of weight loss, better insulin sensitivity, improved dyslipidemia, and reduced inflammatory markers." (PMID 28822064, 2018). "Accumulated evidence shows that healthy muscle strength is closely related to improved insulin sensitivity, modulated insulin secretion, and ameliorated dyslipidemia, the principal risk factors for developing NAFLD." (PMID 30322094, 2018). "Later in life, surviving offspring develop metabolic syndromes associated with increased BA concentrations as well as defect in glucose/insulin homeostasis." (PMID 30443025, 2018). "After adjustment for MVPA, LPA was inversely associated with all-cause mortality risk and was favorably associated with some cardiometabolic risk factors including WC, triglyceride levels, insulin, and the presence of metabolic syndrome." (PMID 29986718, 2018). "One of the central mechanisms of dysfunction is disturbance of the hypothalamic cardiac clock, a consequence of dopamine deficiency that leads to sympathetic dominance, insulin resistance, and features of the metabolic syndrome." (PMID 30210276, 2018). "In the process of treating NAFLD, paying attention to the patients' weight loss, their blood sugar, metabolic syndrome and hyperlipidemia control as well as using antioxidants, such as vitamin E and drugs increasing insulin sensitivity have been recommended." (PMID 29564059, 2018). "Here, we ascertained the role of CRF2 in glucose clearance, insulin sensitivity, and other parameters associated with metabolic syndrome in a mouse model of nutritional stress." (PMID 30400826, 2018). "In metabolic syndrome, EV-associated noncoding RNAs can modulate biological processes (oxidative stress, inflammation, insulin signaling, adipogenesis, and angiogenesis) which can promote disease progression." (PMID 29808089, 2018). "The association between metabolic syndrome and prostate cancer focused on the function of insulin, IGF-1, and their receptors as strategic factors in downstream signaling pathways that stimulate tumor growth." (PMID 29794984, 2018). "The bivariate analysis showed positive associations of the iEAT with gender, age, hypertension, dyslipidemia, smoking, body mass index, waist circumference, insulin dose, and triglyceride (P < 0.05)." (PMID 30526614, 2018). "The mean risk factors of metabolic syndrome was decreased in the metformin-insulin group (2.27 ± 1.13 vs. 2.03 ± 0.94, p = 0.06), whereas it did not change in the insulin alone group (2.31 ± 1.03 vs. 2.20 ± 0.94, p = 0.264)." (PMID 29338714, 2018). "Cardiometabolic risk (CMR) factors, such as elevated cholesterol, dyslipidemia, and insulin insensitivity, are well known to increase the risk of adult cardiometabolic diseases." (PMID 29279776, 2017). "Changes in IMTG were associated with visceral and intermuscular fat, metabolic syndrome, insulin and leptin (p<0.05 for all), however, these associations did not remain after adjustment for visceral fat changes." (PMID 29190720, 2017). "It is well recognized that Insulin sensitivity/resistance is associated with metabolic syndrome tightly." (PMID 28673352, 2017). "ERα plays an important role in maintenance of metabolic homeostasis and insulin sensitivity, with ERα perturbation linked to the metabolic syndrome." (PMID 28473239, 2017). "Each component of metabolic syndrome, which is characterized by reduced insulin sensitivity, is a significant risk factor for CVD." (PMID 28912840, 2017).
metabolic syndrome (continued). "Our study indicates that TNF-α signaling is implicated in cardiac insulin sensitivity regulation, further emphasizing promising therapeutic targets for disease conditions with chronic low-grade inflammation, such as metabolic cardiovascular syndrome." (PMID 28304381, 2017). "Several components of metabolic syndrome at baseline were associated with changes in FS, higher fasting plasma concentrations of insulin being an independent predictor of less favorable change in FS." (PMID 28603501, 2017). "Increased levels of Roseburia were found to be associated with improved insulin sensitivity following gut microbiota transplantations from lean donors to recipients with metabolic syndrome." (PMID 28937612, 2017). "Apart from the achievement of a satisfactory glycemic profile and improvement of the insulin sensitivity pioglitazone use is known to be associated with the amelioration of dyslipidemia in patients with T2DM." (PMID 29163673, 2017). "Visceral fat and liver play central roles on whole-body insulin sensitivity and glucose metabolism and are core drivers of the metabolic syndrome and cardiovascular risk." (PMID 27884961, 2017). "Elevated HR is a strong predictor of cardiovascular disease and metabolic syndrome and is also associated with IR, insulin precursor presence, and the acute insulin response." (PMID 28081144, 2017). "We also measured circulating adiponectin because it is an adipocyte-secreted hormone associated with improved insulin sensitivity and the amelioration of the metabolic syndrome." (PMID 28828264, 2017). "This parameter is also associated with metabolic syndrome, insulin sensitivity, and other age-related functional impairments." (PMID 28455973, 2017). "Each additional 30 min accumulated in short bouts of SB (lasting 1–15 min) was associated with lower BMI, WC and insulin (−0.36 kg/m2, −0.87 cm, and −0.51 mmol/L respectively) and OR 0.71 for metabolic syndrome, all p < 0.05." (PMID 26980183, 2016). "One of the major areas of research in the PCOS-prone JCR:LA-cp rodent model is understanding the distinct mechanisms of androgens and insulin in the cardiometabolic manifestations, particularly dyslipidemia and CVD risk." (PMID 27777929, 2016). "This is of relevance as fat deposition in liver is linked to systemic insulin resistance and the development of metabolic syndrome." (PMID 27885970, 2016). "Multiplying coefficients by 30, each additional 30 min of MVPA was associated with lower BMI, WC, FMI, insulin (−0.69 kg/m2, −2.13 cm, −0.48 kg/m2, −0.78 mmol/L respectively) and OR 0.58 for metabolic syndrome, all p < 0.05." (PMID 26980183, 2016). "Recently, report has been found a low activation state of AMP-activated protein kinase (AMPK) with metabolic disorder associated with impaired insulin sensitivity, fat accumulation and dyslipidemia." (PMID 27322312, 2016). "AEBr induces an antihyperglycemic effect by diminution of glucose levels, an augmentation of insulin, and corrects the dyslipidemia associated with an increase in the high density lipoprotein cholesterol." (PMID 27047569, 2016). "In a very recent study, we have shown that dietary fructose causes an increase in the plasma level of insulin and triglyceride, in association with expansion of omental mass, pointing metabolic syndrome and increased visceral adiposity in male and female rats." (PMID 27066503, 2016). "GDM and preeclampsia, which are considered features of MetS, are associated with exaggerated dyslipidemia, insulin and glucose metabolism abnormalities during and even after pregnancy." (PMID 27006707, 2016).
metabolic syndrome (continued). "Loss of insulin sensitivity triggers fasting hyperglycemia and increases hepatic lipid synthesis, dyslipidemia, hypertension, and fat accumulation in adipose tissues." (PMID 27098727, 2016). "In conclusion, the results from this study indicate that the frequency of coffee consumption had an inverse association with the risk of metabolic syndrome and a direct correlation with insulin sensitivity in Korean women." (PMID 27977716, 2016). "As hyperinsulinaemia underlies metabolic syndrome, we next examined fasting serum insulin levels in FAIM-KO and WT mice." (PMID 26866272, 2016). "FOXO1, which was down-regulated in the group of animals with high CLA-c9t11 content, is highly expressed in tissues such as pancreas, liver, skeletal muscle and adipose tissue in response to insulin and is associated with metabolic disorders as dyslipidemia." (PMID 27875996, 2016). "A meta-analysis of 31 observational studies showed that the TNF-α gene is involved in the pathogenesis of the metabolic syndrome (the 308A variant of this gene has been associated with elevated levels of insulin and blood pressure)." (PMID 27832797, 2016). "Taken all together, most of the associations were consistent with the concept of the metabolic syndrome including insulin, C-peptide, lipids and inflammatory markers." (PMID 27829412, 2016). "In the present analysis, we investigated associations between metabolic syndrome traits and insulin sensitivity and beta-cell function after adjusting for age and sex." (PMID 27597980, 2016). "Here we compared the associations between these specific abdominal fat depots, insulin sensitivity and metabolic syndrome risk." (PMID 26437649, 2015). "The metabolic syndrome traits (blood pressure, lipid profile, fasting glucose and insulin) were measured and the values were combined into a metabolic syndrome risk score." (PMID 26437649, 2015). "The alanine to threonine amino acid substitution at codon 54 (Ala54Thr) of the intestinal fatty acid binding protein (FABP2) has been associated with elevated levels of insulin and blood glucose as well as with dyslipidemia." (PMID 26703680, 2015). "Vitamin D is also involved in glycemic control, lipid metabolism, insulin secretion, and sensitivity, explaining the association between vitamin D deficiency and metabolic syndrome." (PMID 26000280, 2015). "Pharmacological inhibition of sympathetic nerve activity to achieve sustained weight loss and improvements in insulin sensitivity, glucose tolerance, dyslipidemia, and hypertension is currently under intense investigation." (PMID 26064978, 2015). "Our data indicate that AD is a rather common dyslipidemia in childhood; it associates with metabolic abnormalities typical of insulin resistant state and shows a strong familial aggregation." (PMID 25897955, 2015). "Impaired insulin responses in white adipocytes lead to excess circulating lipids, which in turn are associated with inflammatory processes leading to metabolic syndrome." (PMID 26692198, 2015). "Accordingly, resistance training for improving muscle fitness should be performed to prevent or improve metabolic risk factors such as insulin resistance and dyslipidemia." (PMID 26175963, 2015). "In our previous study it was demonstrated that prolonged treatment with GbE promoted a significant visceral adiposity loss, improvement of insulin sensitivity, reduction of dyslipidemia, and stimulation of insulin signaling cascade in gastrocnemius muscle." (PMID 25960614, 2015). "Decreased insulin control of adipocyte lipid storage is an important initiating event leading to metabolic syndrome and associated morbidities." (PMID 26692198, 2015). "The combination of abdominal obesity, impaired glucose and insulin metabolism, dyslipidemia and hypertension is known as metabolic syndrome, an important risk factor for cardiovascular and coronary heart disease mortality." (PMID 25036223, 2014).
metabolic syndrome (continued). "NASH has been reported to be a component of the so-called “metabolic syndrome,” that is, a cluster of closely associated abnormalities related to the insulin-resistant phenotype." (PMID 24987492, 2014). "ESR1 Xbal G alelle was associated to insulin sensitivity and metabolic syndrome in the Study of Women’s Health Across the Nation, but only in Asian ones." (PMID 25077953, 2014). "We have shown support for this concept in overweight Latino adolescents, whereby higher morning serum cortisol levels are associated with metabolic syndrome, and predict future deterioration of insulin sensitivity." (PMID 24433565, 2014). "Adiponectin, adipocytokine encoded by ADIPOQ, is central to insulin sensitivity and resistance and other metabolic syndrome traits in diverse populations." (PMID 25121131, 2014). "Prevention strategies are based on strict glycemic control with intensive insulin treatment, multifactorial intervention, and lifestyle modification including control of hypertension, dyslipidemia, stop smoking, weight loss, and adequate physical exercise." (PMID 25520703, 2014). "In humans high levels of intracellular cortisol can increase glucose output in the liver, induce fat accumulation and weaken insulin sensitivity in adipose tissues, resulting in an increased risk for the metabolic syndrome." (PMID 24404164, 2014). "Accordingly, increased levels of Roseburia were associated with improved insulin sensitivity after gut microbiota transplantations from lean donors to recipients with metabolic syndrome." (PMID 25214711, 2014). "Increase in insulin sensitivity has also been associated with increase in butyrate producing intestinal bacteria in subjects with metabolic syndrome." (PMID 25370913, 2014). "Women who had a fiber bread pattern had a lower prevalence of metabolic syndrome and higher insulin sensitivity, while a white bread pattern was positively associated with metabolic syndrome and lowered insulin sensitivity." (PMID 25365577, 2014). "Vascular insufficiency, ischemia, hypoxia, dyslipidemia, metabolic syndrome, and impaired insulin signaling are implicated in the development and progression of DN." (PMID 24936198, 2014). "Regular physical activity has beneficial effects on metabolic syndrome as it has been shown that physical activity is associated with better insulin sensitivity and a reduction in diastolic blood pressure." (PMID 25437226, 2014). "Recent animal studies have also suggested that hepatic insulin resistance and hepatic inflammation can also contribute to the development of dyslipidemia and increased cardiovascular disease risk." (PMID 25126490, 2014). "Recent evidence has implicated a direct role of disturbed Wnt signaling on metabolic syndrome including obesity, insulin resistence and T2DM." (PMID 24404139, 2014). "Supplementation with olive leaf polyphenols for 12 weeks significantly improved insulin sensitivity and pancreatic β-cell secretory capacity in overweight middle-aged men at risk of developing the metabolic syndrome." (PMID 23516412, 2013). "Polygenetically inherited metabolic syndrome of WOKW rats is associated with enhanced autophagy in insulin resistant adipose tissue." (PMID 23668414, 2013). "In the current study, only those who were insulin resistant showed evidence of dyslipidemia, however causality cannot be inferred." (PMID 23855321, 2013). "The data also suggests that interindividual variation in dyslipidemia and insulin sensitivity is associated with the ratio of the adipokines." (PMID 23533722, 2013). "Predicted targets of miRNAs were found to be enriched in metabolic pathways like insulin-pathway but also in heart-associated and neurological contexts, indicating a potential role for curcumin in managing metabolic syndrome." (PMID 24349037, 2013).